RN7SKP165 (RN7SK pseudogene 165)
Gene: Miscellaneous RNA gene on chromosome 1 (226,445,937 to 226,446,292, forward strand). Ensembl gene ENSG00000223282.
Homologues: Orthologues: chimpanzee 7SK (86% identical), guinea pig 7SK (59% identical). Paralogues in human: 7SK (65% identical), RN7SKP189 (65% identical), RN7SKP203 (65% identical), RN7SKP208 (65% identical), RN7SKP127 (64% identical), RN7SKP180 (64% identical), RN7SKP176 (64% identical), RN7SKP71 (64% identical), RN7SKP149 (64% identical), RN7SKP217 (64% identical), RN7SKP133 (63% identical), RN7SKP237 (63% identical), and 284 more.